ATP4B (ATPase H+/K+ transporting subunit beta)
Description:
The beta subunit of the gastric H(+)/K(+) ATPase pump which transports H(+) ions in exchange for K(+) ions across the apical membrane of parietal cells. Plays a structural and regulatory role in the assembly and membrane targeting of a functionally active pump (By similarity). Within a transport cycle, the transfer of a H(+) ion across the membrane is coupled to ATP hydrolysis and is associated with a transient phosphorylation of the alpha subunit that shifts the pump conformation from inward-facing (E1) to outward-facing state (E2). Interacts with the phosphorylation domain of the alpha subunit and functions as a ratchet, stabilizing the lumenal-open E2 conformation and preventing the reverse reaction of the transport cycle (By similarity).
Synonyms: ATP6B
Tractability: Small molecule: an approved drug acts on it; it belongs to a druggable protein family. Antibody: its Gene Ontology location is reachable by antibodies, with high confidence; UniProt places it where antibodies can reach, with medium confidence; UniProt predicts a signal peptide or a membrane-spanning region; the Human Protein Atlas places it where antibodies can reach. PROTAC: ubiquitination databases record sites on it.
Gene: Protein-coding gene on chromosome 13 (113,648,804 to 113,658,198, reverse strand). Ensembl gene ENSG00000186009.
Subcellular location: Apical cell membrane; Cell membrane
Subcellular location (Human Protein Atlas): Plasma membrane
Pathways (Reactome):
Transport of small molecules: Ion transport by P-type ATPases
Gene Ontology:
Molecular function: protein binding; ATPase activator activity; P-type potassium:proton transporter activity; heterocyclic compound binding
Biological process: intracellular potassium ion homeostasis; intracellular sodium ion homeostasis; potassium ion import across plasma membrane; sodium ion export across plasma membrane; pH reduction; potassium ion transport; proton transmembrane transport; response to lipopolysaccharide; sodium ion transport
Cellular component: apical plasma membrane; plasma membrane; sodium:potassium-exchanging ATPase complex
Genetic constraint (gnomAD): Loss-of-function variants: 27 observed, 35.81 expected, observed/expected ratio (o/e) 0.75, 90% interval 0.56 to 1.04. The upper end of that interval is the gene's LOEUF score, 1.04, which puts it in group 4 of 6, group 1 being the genes least tolerant of losing a copy. Missense variants: 375 observed, 379.26 expected, observed/expected ratio (o/e) 0.99, 90% interval 0.91 to 1.08. Synonymous variants: 162 observed, 155.02 expected, observed/expected ratio (o/e) 1.04, 90% interval 0.92 to 1.19.
Homologues: Orthologues: chimpanzee ATP4B (99% identical), macaque ATP4B (97% identical), pig ATP4B (85% identical), rabbit ATP4B (84% identical), mouse Atp4b (84% identical), dog ATP4B (83% identical), guinea pig ATP4B (82% identical), rat Atp4b (82% identical), tropical clawed frog atp4b (52% identical), Drosophila melanogaster CG33310 (24% identical). Paralogues in human: ATP1B2 (38% identical), ATP1B3 (34% identical), ATP1B4 (34% identical), ATP1B1 (32% identical).
Diseases named in the same sentence as ATP4B in open-access papers:
ATP4B is named in the same sentence as 25 diseases in open-access papers, as found by Europe PMC text mining. Sharing a sentence is not in itself a finding about the gene and the disease. The quoted sentences say what the papers report.
gastric cancer (16 papers, 2013 to 2025). A primary or metastatic malignant neoplasm involving the stomach. "Of note, the down-regulation of ATP4A or ATP4B expression has been associated with gastric cancer prognosis." (PMID 35741779, 2022). "ATP4B level decreases progressively with the advancement of gastric mucosal atrophy and intestinal metaplasia, and is markedly down‐regulated during the process of carcinogenesis, providing further evidence supporting ATP4B as a sensitive and reliable diagnostic marker for gastric cancer." (PMID 41114471, 2025). "The areas under the curve (AUCs) were 0.7786 and 0.7496 for ATP4A and ATP4B mRNA, respectively (95% CI, 0.6885‒0.8687 and 0.6452‒0.8540, respectively), suggesting its potential utility as a biomarker for gastric cancer." (PMID 41114471, 2025). "In conclusion, three hub genes (ATP4A, ATP4B, and ESRRG) closely related to gastric cancer were mined, based on which the ML diagnostic model of gastric cancer was conducted." (PMID 35812327, 2022). "Meanwhile, ATP4A and ATP4B downregulation involve DNA methylation and methylated ATP4B DNA in the plasma are potential biomarkers for gastric cancer." (PMID 32596394, 2020). "We also identified three LSL-hMYH9; Atp4b-cre; Tff1-/- mice with advanced gastric cancer, suggesting that hMYH9 promoted GC progression." (PMID 32685004, 2020). "Bioinformatics analysis showed that lncRNA MEG3 and ATP4B were downregulated in gastric cancer tissues compared with normal tissues." (PMID 31584879, 2019). "Studies have shown that ATP4B is expressed at low levels in gastric cancer tissues compared with normal tissues." (PMID 31584879, 2019). "We identified REG1A, CHGA, TFF2, ATP4A and ATP4B to be downregulated in intestinal gastric cancer, and Rajkumar and co-workers found ATP4A and ATP4B to be downregulated in gastric tumor tissues compared to normal tissues." (PMID 29484116, 2018). "To further verify the level of ATP4B in gastric cancer, we analyzed 24 non‐tumor gastric mucosal biopsy specimens and the tumor‐adjacent tissues of 24 ESD specimens, with four different stages of gastritis with intestinal metaplasia (IM), 6 specimens for each stage." (PMID 41114471, 2025). "The downregulation of ATP4B in plasma is a marker for gastric cancer." (PMID 38698303, 2024). "Studies have shown that miR-181a-5p is upregulated in gastric cancer patients and that ATP4B is downregulated in the plasma of gastric cancer patients and could act as a biomarker." (PMID 31584879, 2019). "In addition, studies have explored the possibility of ATP4B as a biomarker for gastric cancer screening, verifying the possibility of early diagnosis of gastric cancer through screening of plasma expression." (PMID 31584879, 2019). "Many studies have revealed that ATP4B expression is decreased in human gastric cancer (GC), and some studies have reported abnormal expression of ATP4B in other diseases such as human hepatocellular carcinoma (HCC), laryngopharyngeal reflux, and laryngeal cancer." (PMID 33902636, 2021). "Network analysis showed that ATP4B and MEG3 have the same expression trend in gastric cancer and are closely related." (PMID 31584879, 2019). "In this paper, the differentially expressed lncRNAs and mRNAs in gastric cancer patients were analyzed by using data from the TCGA database, and MEG3 and ATP4B were significantly downregulated." (PMID 31584879, 2019). "Here, we describe morphological and molecular alterations in gastric mucosa of slc26a9−/− mice and in selective parietal cell-deleted slc26a9fl/fl/Atp4b-Cre mice and correlate SLC26A9 expression levels with morphological and clinical parameters in a cohort of gastric cancer (GC) patients." (PMID 35426084, 2022).
gastric cancer (continued). "Compared with the normal samples, the results demonstrated that ATP4B, TFF2, GIF, GKN1, and TFF2 were low expressed in tumor samples, suggesting these targets might act as the TSGs in gastric cancer." (PMID 36428568, 2022).
gastric tumors (3 papers, 2012 to 2021). "Together, these staining results indicate IM in Atp4b-cre; MycOE mice and suggest that c-Myc-driven gastric tumors share similarities with intestinal-type GC." (PMID 33259779, 2021).
pancreatic cancer (2 papers, 2015 to 2020). "Furthermore, our recent data mining analyses indicate that on the mRNA level ATP4A and ATP4B are down-regulated in pancreatic cancer." (PMID 25993003, 2015).
anemia (1 paper, 2024). A reduction in the number of red blood cells, the amount of hemoglobin, and/or the volume of packed red blood cells. "Increased ATP4A and ATP4B antibody levels were found in patients with PCAs and in subjects with a clinical suspicion of gastric body atrophy (presence of dyspepsia, anemia, and histological findings of a concomitant Helicobacter pylori infection)." (PMID 39202208, 2024).
atrial fibrillation (1 paper, 2013). A disorder characterized by an electrocardiographic finding of a supraventricular arrhythmia characterized by the replacement of consistent P waves by rapid oscillations or fibrillatory waves that vary in size, shape and timing and are accompanied by an irregular ventricular response. "We demonstrate the use of our algorithm to predict novel candidate genes for human atrial fibrillation (such as HRH2, ATP4A, ATP4B, and HOPX) and epilepsy (e.g., PAX6 and NKX2-1)." (PMID 23800157, 2013).
autoimmune conditions (1 paper, 2012). "Based on the literature, autoantibodies were also tested against six potential organ–specific antigens implicated in T1D and/or other autoimmune conditions including ATP4B, TGM2, TPO, KCNRG, AQP-4, and GFAP." (PMID 23028856, 2012).
autoimmune gastritis (1 paper, 2023). Inflammation of the body fundic mucosa of the stomach. "Researchers have developed luciferase immunoprecipitation assays targeting ATP4A and ATP4B and have demonstrated favorable diagnostic accuracy in patients with histologically confirmed autoimmune gastritis." (PMID 37504250, 2023).
gastric adenoma (1 paper, 2021). A neoplastic polyp that arises from the stomach. "We found that overexpression of c-Myc in Atp4b+ gastric parietal cells could induce gastric adenoma in mice." (PMID 33259779, 2021).
hypopharyngeal carcinoma (1 paper, 2022). Carcinoma, predominantly squamous cell, arising from the epithelial cells of the hypopharynx. "Hypopharyngeal carcinoma FaDu cells expressing H+/K+-ATPase α, β (ATP4A and ATP4B) induced mitochondrial damage and the expression of related genes." (PMID 35083516, 2022).
neuroendocrine tumors (1 paper, 2012). "Next to small ATP4B- and TAg-positive tumors, ATP4B-negative invasive neuroendocrine tumors develop after a long latency period of more than 300 days." (PMID 22253802, 2012).
tumor (12 papers, 2010 to 2025). "To explore the potential mechanism underlying c-Myc-mediated tumor growth, we performed RNA sequencing with gastric tissues from WT and Atp4b-cre; MycOE mice." (PMID 33259779, 2021). "We found that the tumor incidence in Myh9fl/fl; Atp4b-cre; Tff1-/- mice was significantly reduced (5/20, 25%) and the tumor size was smaller, when compared with Myh9fl/fl; Tff1-/- mice (8/20, 40%)." (PMID 32685004, 2020). "In addition, qRT-PCR results showed lower expression of ATP4B in tumor tissues compared to normal tissues (P<0.01)." (PMID 31584879, 2019). "Both these genes were oncogenes, and downregulated genes such as ATP4A, ATP4B, PGA3, PGA4, and PGA5 were reported tumor suppressors in GC." (PMID 39283078, 2024). "Conversely, the tumor incidence in LSL-hMYH9; Atp4b-cre; Tff1-/- mice was significantly enhanced (16/20, 80%) and the tumor size was larger, when compared with LSL-hMYH9; Tff1-/- mice (9/20, 45%)." (PMID 32685004, 2020). "We observed that the expressions of ESSRG, ATP4A, and ATP4B in tumor samples were significantly lower than those in normal ones." (PMID 35812327, 2022).
cancer (6 papers, 2018 to 2024). A tumor composed of atypical neoplastic, often pleomorphic cells that invade other tissues. "Nevertheless, poorly differentiated carcinoma was observed in Slc26a9fl/fl/Atp4b-Cre mice at 18 months, which was accompanied by loss of MUC5AC and Claudin 18.2 expression compared with that in Slc26a9fl/fl littermates." (PMID 35426084, 2022). "First, we validated our predictions in cancer tissues and found that miR-181a-5p was upregulated and ATP4B expression was downregulated in GC tissues." (PMID 31584879, 2019). "However, this does not point to Atp4b-expressing parietal cells as the source of these cancers, since Cre is expressed constitutively from the fetal phase and oncogenic alterations likely change the cell fate of Atp4b-Cre-expressing fetal progenitors into stem-like cells." (PMID 30384487, 2018).
infection (2 papers, 2015 to 2017). The state of being infected such as from the introduction of a foreign agent such as serum, vaccine, antigenic substance or organism. "We observed downregulation of Atp4a and Atp4b in response to infection with H. felis, which may represent a loss of parietal cells that has been shown to precede gastric dysplasia." (PMID 28201999, 2017).
ATP4B also shares sentences with these, for which no sentence is quoted: Acidosis (1 paper); dyspepsia (1); epilepsy (1); Esophageal stricture (1); gastritis (1); HCMV infection (1); hepatocellular carcinoma (1); laryngeal carcinoma (1); Laryngopharyngeal Reflux (1); lung carcinoma (1); osteoporosis (1); signet ring cell carcinoma (1).